LEP (leptin)
Diseases named in the same sentence as LEP in open-access papers (continued):
Sharing a sentence is not in itself a finding about the gene and the disease.
breast cancer (continued). "A crosstalk between Notch, IL-1, and leptin signaling (NILCO) has been associated with breast cancer growth." (PMID 28659656, 2017). "Our subgroup analysis suggested that adiponectin, leptin and resistin were associated with incidence of breast cancer in both pre- and postmenopausal women." (PMID 29088874, 2017). "Recent study reported that leptin signaling contributes to the metabolic features associated with breast cancer malignancy, such as switching the cells' energy balance from mitochondrial β-oxidation to the aerobic glycolytic pathway." (PMID 26904147, 2016). "This study aims to explore the effect of leptin on EMT in breast cancer cells and the underlying mechanism." (PMID 27769315, 2016). "In recent years, most studies concern leptin gene polymorphism involvement in breast cancer, including rs2060713C/T, rs7799039, G-2548A, G-223A, G-2549A." (PMID 26825898, 2016). "We stratified between Leptin (-2548G/A) gene polymorphism and clinico-pathological parameters and habits of the breast cancer patients based on the dominant models." (PMID 26825898, 2016). "This meta-analysis was conducted to systematically get a more accurate estimation of the association between the Leptin (-2548G/A) gene polymorphism and breast cancer risk." (PMID 26825898, 2016). "As an important regulator of the crosstalk between breast cancer cells and CAFs, the cytokine leptin has been associated to breast carcinogenesis." (PMID 26899873, 2016). "We found that Leptin-2548G/A A > G variant had a significantly increased risk of breast cancer in overall population." (PMID 26825898, 2016). "Seven articles, including 3278 cases and 2682 controls, were used to investigate the association of the Leptin (-2548G/A) gene polymorphism with breast cancer susceptibility in Caucasians." (PMID 26825898, 2016). "In summary, our present meta-analysis provides evidence of the association between Leptin-2548G/A gene polymorphism and breast cancer risk, and suggests that Leptin-2548G/A gene polymorphism has an increased risk with breast cancer." (PMID 26825898, 2016). "A meta-analysis of Niu et al41 suggested that the leptin level plays a role in breast cancer and has potential for development as a diagnostic tool." (PMID 26825898, 2016). "In summary, our findings suggest that variation in genes in the insulin, IGF, GH, and LEP pathways contribute to the risk of breast cancer and, in particular, to ER-negative breast cancer in African-American women." (PMID 27942580, 2016). "A total of 9 case-control studies on Leptin (-2548G/A) gene polymorphism and breast cancer risk, including 3725 cases and 3093 case-free controls were identified." (PMID 26825898, 2016). "In breast cancer, leptin has been associated with increased angiogenesis and vascular endothelial growth factor (VEGF) one of the most potent stimulators of angiogenesis." (PMID 27059487, 2016). "In conclusion, our meta-analysis suggests that the Leptin (-2548G/A) gene polymorphism plays an important role in breast cancer susceptibility, especially in Caucasian." (PMID 26825898, 2016). "We conducted gene-based analyses of 184 genes in the insulin/IGF, growth hormone, and leptin pathways to identify genetic variation associated with risk of breast cancer overall, and for estrogen receptor (ER) subtypes." (PMID 27942580, 2016). "The current study investigated the molecular mechanism underlying leptin-mediated macrophage-breast cancer interaction." (PMID 27588409, 2016). "High body mass index (BMI) results in an increased production of hormones (estrogens, insulin, leptin), and pro-inflammatory cytokines, which have, in turn, been associated with breast cancer risk." (PMID 27464488, 2016). "This study aims to investigate the mechanisms underlying leptin-mediated crosstalk between tumor-associated macrophages (M2 macrophages) and breast cancer cells." (PMID 27588409, 2016).
breast cancer (continued). "This study compared the pattern of change in plasma leptin and adiponectin in overweight-to-obese post-menopausal breast cancer survivors during weight loss." (PMID 26132992, 2015). "Adipose tissues secrete ADIPOQ and LEP-ADIPOQ axis has been well implicated in breast cancer tumorigenesis." (PMID 25923423, 2015). "Leptin has been reported to regulate many signaling pathways and transcription factors implicated in breast cancer stem cells (BCSCs)." (PMID 26359358, 2015). "Many studies have investigated leptin as a risk factor for breast cancer mainly in postmenopausal women, with conflicting and opposing findings." (PMID 26560078, 2015). "Both leptin and its receptor (ObR) are overexpressed in breast cancer, especially in higher grade tumours and are associated with distant metastasis 9,10." (PMID 25721149, 2015). "Studies from our lab and others have established that high leptin levels (hyperleptinemia) associated with obese state stimulate breast cancer cell proliferation, invasion, migration, and angiogenesis, thereby promoting breast tumor growth and metastasis." (PMID 26359358, 2015). "Although data are diverse, studies have provided evidence that increased expression of leptin in patients with breast cancer is associated with large tumor size, advanced tumor stage, high tumor grade and lymph node metastasis." (PMID 26560078, 2015). "Recent studies have shown that polymorphisms in leptin and leptin receptor genes are associated with increased risk for breast cancer." (PMID 26199932, 2015). "We and others have established that high leptin levels (hyperleptinemia) associated with obese state stimulate breast cancer cell proliferation, invasion, migration, and angiogenesis, thereby promoting breast tumor growth and metastasis." (PMID 26036628, 2015). "This study aimed at investigating -2548 G/A polymorphism in leptin gene and Q223R polymorphism in leptin receptor gene in patients with breast cancer." (PMID 26199932, 2015). "Higher leptin level has been shown to be present in various tumors and is linked with tumor progression in colon, prostate and breast cancer." (PMID 25026276, 2014). "Previous studies tend to show a positive association between circulating leptin and breast cancer, although the data for premenopausal women have varied." (PMID 24790820, 2014). "We also found that the level of leptin in breast cancer-associated adipose tissue increased while adiponectin decreased." (PMID 25291184, 2014). "Leptin, the major adipokine secreted by adipose tissue, is also produced by malignant cells, and linked to increased levels of Notch and survivin in breast cancer, and can affect tumor angiogenesis." (PMID 24716804, 2014). "Based on the findings obtained on growth inhibition following treatment with 1,600 ng/ml leptin, cell signaling and cell cycle changes were assessed to determine the underlying mechanisms responsible for growth inhibition in the two breast cancer cell lines." (PMID 24959279, 2014). "The increased levels of leptin and pro-inflammatory cytokines are directly associated with breast cancer development." (PMID 25338520, 2014). "A number of studies support the association between high LEPR/leptin expression and breast cancer progression, metastasis and ER-negativity." (PMID 25482303, 2014). "Notch, IL-1 and leptin are known pro-angiogenic factors linked to breast cancer development, tumor aggressiveness and poor prognosis." (PMID 24716804, 2014). "In this study, we performed a meta-analysis to assess the association between serum leptin level and breast cancer risk." (PMID 23826274, 2013). "As it will further be discussed, leptin-mediated upregulation of IL-1 and Notch systems in breast cancer cells was closely linked to regulation of VEGF and VEGFR2." (PMID 24202338, 2013). "Independent effect of CRP and alterations in the levels of both leptin and adiponectin were altogether accompanied by an increase in breast cancer risk incidence." (PMID 23374911, 2013).
breast cancer (continued). "More data from longitudinal studies is required to clarify the relationships between serum leptin level and breast cancer risk." (PMID 23826274, 2013). "Leptin-induced Notch was linked to the increase of breast cancer cell proliferation, migration, and angiogenic differentiation of endothelial cells." (PMID 24202338, 2013). "This meta-analysis suggests that leptin level plays a role in breast cancer and has potential for development as a diagnostic tool." (PMID 23826274, 2013). "Contradictory results have been reported regarding the association between leptin level and breast cancer." (PMID 23826274, 2013). "Leptin expression has been associated with breast cancer, hepatocellular carcinoma and ovarian cancer." (PMID 24023638, 2013). "Obese postmenopausal women typically have altered serum levels of metabolic hormones, such as insulin, insulin-like growth factor (IGF)-1, leptin, resistin and adiponectin, and are at increased risk for developing breast cancer." (PMID 23840816, 2013). "On the other hand, leptin is also associated with malignancy development, in particular, in breast cancer." (PMID 22929622, 2012). "The insulin-leptin-adiponectin axis has been implicated mechanistically in breast cancer tumorigenesis." (PMID 22295251, 2012). "Leptin has been shown to be associated with breast cancer risk, and has been observed to be differentially expressed in serum of breast cancer and control subjects." (PMID 23202969, 2012). "Clinical studies have reported a positive association between circulating blood leptin and breast cancer risk with particular elevation of mRNA expression in adipocytes in close proximity to the tumor." (PMID 22295251, 2012). "Epidemiological, animal, and in vitro studies have demonstrated that leptin is associated with breast cancer, prostate cancer, gynecological cancers, gastrointestinal cancers, and leukemia." (PMID 22853725, 2012). "Elevated levels of leptin/Ob-R in breast cancer are commonly linked to more invasive tumours and worse prognosis." (PMID 21139583, 2011). "These obese mice with deficiency in leptin signalling show a significantly lower incidence of mammary tumours than their lean littermates." (PMID 21139583, 2011). "Leptin is a growth and pro-angiogenic factor whose signals are strongly linked to the growth of solid tumors, particularly, breast cancer." (PMID 21731759, 2011). "MMTV/TGF-α mice have a proclivity to develop mammary tumours, but when crossed with leptin/Ob-R-deficient mice, there is a reduced incidence of mammary tumours in their progeny." (PMID 21139583, 2011). "On the other hand, MMTV-TGF-α mice have a proclivity to develop mammary tumors, but when crossed with leptin/OB-R deficient mice, there is a reduced incidence of tumors in their progeny." (PMID 21731759, 2011). "Overall, higher leptin concentrations were significantly associated with an increased risk of breast cancer (OR (95% CI) for top vs bottom tertile of leptin was 1.63 (1.07–2.49), Ptrend=0.009)." (PMID 19223908, 2009). "Although leptin has been shown to be correlated with breast cancer risk in this study and earlier reports, contradictory results were also documented by other investigators." (PMID 19223908, 2009). "This is of special interest because altered levels of leptin and adiponectin are consistent with the elevated breast cancer risk in addition to the independent effect of CRP in enhancing the breast cancer risk." (PMID 19545451, 2009). "In this study, we found a significant increase in the risk of breast cancer associated with a high plasma level of leptin." (PMID 19223908, 2009). "The present case–control study was to investigate the relationships of plasma leptin level and anthropometric measures of adiposity with the risk of breast cancer." (PMID 19223908, 2009).
breast cancer (continued). "In 59 breast cancers, the presence of leptin was correlated with ObR (the overall association was about 93%)." (PMID 18945363, 2008). "It is possible that the leptin polymorphism is in linkage disequilibrium with other genes that play a role in breast cancer risk." (PMID 19017403, 2008). "Other studies demonstrated leptin are inversely related to breast cancer risk among premenopausal women." (PMID 21566743, 2008). "Some investigators have examined the relationship between variants of the LEPR Gln223Arg polymorphism and serum levels of leptin since there is some evidence associating serum leptin levels with breast cancer risk." (PMID 19017403, 2008). "Both leptin and leptin receptor have recently been implicated in processes leading to breast cancer initiation and progression in animal models and humans." (PMID 19017403, 2008). "Much has been said about the mechanisms of leptin-induced carcinogenesis in animal models and correlation of serum leptin levels with breast cancer risk." (PMID 19017403, 2008). "Leptin, a protein secreted primarily from adipose tissue, also has been implicated as a mammary tumor (MT) growth factor." (PMID 18162139, 2007). "Additionnaly, in breast cancer it has been shown that a high leptin serum level is associated with reduced OVS." (PMID 16504019, 2006). "A recent large study has demonstrated that subjects with elevated serum leptin levels displayed increased risk of developing breast cancer than those with the normal levels." (PMID 16504019, 2006). "We examined the association between leptin plasma levels and mammographic density, a biomarker for breast cancer risk." (PMID 17010200, 2006). "Other lines of evidence derive from studies on markers of tumoral risk that are elevated in breast cancer, that can upregulate leptin production." (PMID 16504019, 2006). "A significantly higher risk for breast cancer was observed for carriers of LEP (-2548) AA genotype (Odds Ratio (OR) = 3.17; P = 0.001) and carriers of LEP (-2548) GA genotype (OR = 1.45; P = 0.04)." (PMID 16504019, 2006). "Individuals homozygous for LEP (-2548) A have more than 3-fold risk to develop breast carcinoma (OR = 3.17; P = 0.001) compared with individuals homozygous for LEP (-2548) G allele." (PMID 16504019, 2006). "The present case/control study showed a substantially increased risk of breast carcinoma associated in a dose-dependent manner, with the inheritance of the LEP (-2548) A allele." (PMID 16504019, 2006). "A significantly increased risk of breast carcinoma was associated with heterozygous LEP (-2548) GA (OR = 1.45; P = 0.04) and homozygous LEP (-2548) AA (OR = 3.17; P = 0.001) variants." (PMID 16504019, 2006). "Leptin levels correlate strongly with BMI, also during pregnancy, and leptin is suggested to increase breast cancer risk." (PMID 15498103, 2004). "Similarly, leptin promotes inflammation and positively correlates with increased breast cancer risk." (PMID 40034592, 2025). "Moreover, a randomized controlled trial reported that aerobic exercise reduced leptin levels and the risk of breast cancer in a dose-dependent manner." (PMID 38238841, 2024). "The adiponectin/leptin ratio (A/L ratio) is thought to serve as an indicator of adipose tissue dysfunction, and an elevated ratio is linked to lower risks of atherosclerosis and certain cancers, like breast cancer." (PMID 38339282, 2024). "Unfavourable outcomes for breast cancer have been linked to both low adiponectin levels and increased leptin levels, and it is speculated that the adiponectin:leptin ratio may be more important for breast cancer growth than the absolute levels." (PMID 39251829, 2024). "LEP has been implicated in breast cancer, prostate cancer, and diffuse large B-cell lymphoma." (PMID 37282602, 2023). "Thus, besides leptin alone, the adiponectin/leptin ratio is also associated with indication of breast cancer progression." (PMID 37181043, 2023).
breast cancer (continued). "Leptin was closely associated with post-chemotherapy fatigue in breast cancer patients." (PMID 37542585, 2023). "Epidemiological evidence supports that a higher leptin level was associated with a higher risk of recurrence in all breast cancer patients, and a lower adiponectin level was associated with a higher risk of recurrence in hormone receptor-negative breast cancer patients." (PMID 37571390, 2023). "Additionally, leptin promotes the production of IL-18 and IL-8, which interfere with breast cancer cells and M2 tumor-associated macrophages, and thus stimulates tumor growth." (PMID 38202341, 2023). "Taking these possible reasons into consideration, we in this meta-analysis tested the hypothesis that genes encoding leptin and adiponectin and their receptors are potential candidates to breast cancer." (PMID 37274250, 2023). "Leptin, which is associated with estrogen, also contributes to breast cancer." (PMID 36755926, 2023). "Women with elevated serum leptin have a higher risk of breast cancer." (PMID 36835413, 2023). "High levels of leptin have been associated with an increased risk of breast cancer as well as with a worse prognosis; however, low levels of ghrelin are associated with increased expression of aromatase in adipose tissue and thus with an increased risk of breast cancer." (PMID 36839371, 2023). "Some adipokines expression levels in serum, like resistin, leptin, adiponectin, and visfatin, can serve as risk factors for clinicopathological features of post-menopausal breast cancer, including tumor-node-metastasis (TNM) stage, tumor size, LN metastasis, and histological grade." (PMID 35701840, 2022). "Whether this local increase in leptin contributes to the elevated risk of breast cancer is uncertain but warrants further consideration." (PMID 35087024, 2022). "For instance, leptin is inversely related to breast cancer risk in premenopausal women." (PMID 35628510, 2022). "It is suggested that the increase in circulating leptin could enhance the risk of developing breast cancer when the secretion of proinflammatory cytokines (IL-6, IL-1, IL-17, TNF-α and TGF-β-) is stimulated as well secreted by adipocytes." (PMID 36142655, 2022). "Moreover, leptin is secreted from cancer-associated fibroblasts (CAFs) which are located in the tumor microenvironment and continuously interact in crosstalk with breast cancer cells." (PMID 36401194, 2022). "The expression of leptin, adiponectin, and resistin, which represent classic adipokines, and their differential expression in association with clinicopathological parameters have been largely studied in breast cancer." (PMID 36077676, 2022). "However, the role of leptin in regulating breast cancer cell proliferation has also been associated with a shift in ATP production from glycolysis to mitochondria and with an improvement in mitochondrial quality, function and biogenesis." (PMID 36361728, 2022). "Breast cancer recurrence was negatively associated only with post-treatment leptin concentration." (PMID 36556428, 2022). "Postmenopausal women with an increased risk of breast cancer show improved hormonal (bioavailable estradiol, testosterone, and insulin) and adipocytokine (relative adiponectin/leptin, C-reactive protein) markers of breast cancer in serum and breast tissue with weight loss of more than 10%." (PMID 35752704, 2022). "One of the most relevant adipokines is leptin, which is closely associated with breast cancer." (PMID 34868066, 2021). "Accordingly, elevated leptin levels are positively associated with breast cancer risk." (PMID 33859943, 2021).